GABBR2 (gamma-aminobutyric acid type B receptor subunit 2)
Description:
Component of a heterodimeric G protein-coupled receptor for GABA, formed by GABBR1 and GABBR2. Within the heterodimeric GABA receptor, only GABBR1 seems to bind agonists, while GABBR2 mediates coupling to G proteins. Ligand binding causes a conformation change that triggers signaling via guanine nucleotide-binding proteins (G proteins) and modulates the activity of down-stream effectors, such as adenylate cyclase. Signaling inhibits adenylate cyclase, stimulates phospholipase A2, activates potassium channels, inactivates voltage-dependent calcium-channels and modulates inositol phospholipid hydrolysis. Plays a critical role in the fine-tuning of inhibitory synaptic transmission. Pre-synaptic GABA receptor inhibits neurotransmitter release by down-regulating high-voltage activated calcium channels, whereas postsynaptic GABA receptor decreases neuronal excitability by activating a prominent inwardly rectifying potassium (Kir) conductance that underlies the late inhibitory postsynaptic potentials. Not only implicated in synaptic inhibition but also in hippocampal long-term potentiation, slow wave sleep, muscle relaxation and antinociception (Probable).
Synonyms: GABABR2; GPR51; GPRC3B; HG20; DEE59; EIEE59; HRIHFB2099; NDPLHS
Tractability: Small molecule: an approved drug acts on it; a structure with a bound ligand is known; a high-quality ligand is known; it belongs to a druggable protein family. Antibody: UniProt places it where antibodies can reach, with high confidence; its Gene Ontology location is reachable by antibodies, with high confidence; UniProt predicts a signal peptide or a membrane-spanning region. PROTAC: ubiquitination databases record sites on it; its protein half-life has been measured; a small molecule that binds it is known.
Target class: Small molecule receptor (family C GPCR); GABA-B receptor; Membrane receptor; Neurotransmitter receptor (family C GPCR); Family C G protein-coupled receptor
Gene: Protein-coding gene on chromosome 9 (98,288,096 to 98,709,739, reverse strand). Ensembl gene ENSG00000136928.
Subcellular location: Cell membrane; Postsynaptic cell membrane
Pathways (Reactome):
Neuronal System: Activation of G protein gated Potassium channels; GABA B receptor activation; Inhibition of voltage gated Ca2+ channels via Gbeta/gamma subunits
Signal Transduction: Class C/3 (Metabotropic glutamate/pheromone receptors); G alpha (i) signalling events
Gene Ontology:
Molecular function: G protein-coupled GABA receptor activity; protein binding; protein heterodimerization activity; transmembrane signaling receptor activity; G protein-coupled receptor activity; GABA receptor activity
Biological process: adenylate cyclase-inhibiting G protein-coupled receptor signaling pathway; gamma-aminobutyric acid signaling pathway; chemical synaptic transmission; G protein-coupled receptor signaling pathway; negative regulation of adenylate cyclase activity; neuron-glial cell signaling; synaptic transmission, GABAergic
Cellular component: G protein-coupled GABA receptor complex; G protein-coupled receptor heterodimeric complex; GABA receptor complex; plasma membrane; postsynaptic membrane; cytoplasm; membrane; neuron projection
Genetic constraint (gnomAD): Loss-of-function variants: 16 observed, 61.64 expected, observed/expected ratio (o/e) 0.26, 90% interval 0.17 to 0.39. The upper end of that interval is the gene's LOEUF score, 0.39, which puts it in group 1 of 6, group 1 being the genes least tolerant of losing a copy. Missense variants: 511 observed, 836.19 expected, observed/expected ratio (o/e) 0.61, 90% interval 0.57 to 0.66. Synonymous variants: 342 observed, 333.64 expected, observed/expected ratio (o/e) 1.03, 90% interval 0.94 to 1.12.
Gene-disease validity (ClinGen):
ClinGen rates the evidence that GABBR2 causes each of these diseases.
complex neurodevelopmental disorder (autosomal dominant): Moderate. A disorder that involves more than one phenotype associated with the central nervous system, including but not limited to intellectual disability, autism, and seizures (epilepsy).
Homologues: Orthologues: chimpanzee GABBR2 (100% identical), macaque GABBR2 (99% identical), pig GABBR2 (99% identical), mouse Gabbr2 (98% identical), rat Gabbr2 (98% identical), dog GABBR2 (91% identical), guinea pig GABBR2 (86% identical), rabbit GABBR2 (85% identical), tropical clawed frog gabbr2 (85% identical), zebrafish gabbr2 (75% identical), Drosophila melanogaster GABA-B-R2 (38% identical), Caenorhabditis elegans gbb-2 (29% identical). Paralogues in human: GABBR1 (31% identical), GPR156 (13% identical).
Diseases named in the same sentence as GABBR2 in open-access papers:
GABBR2 is named in the same sentence as 85 diseases in open-access papers, as found by Europe PMC text mining. Sharing a sentence is not in itself a finding about the gene and the disease. The quoted sentences say what the papers report.
epilepsy (17 papers, 2015 to 2026). A brain disorder characterized by episodes of abnormally increased neuronal discharge resulting in transient episodes of sensory or motor neurological dysfunction, or psychic dysfunction. "GABBR2 was found to be differentially expressed in MDS cells and mutations of GABBR2 have been identified in various epilepsies, leading to neuronal hyperexcitability and seizures." (PMID 40806509, 2025). "The histological phenotype of the Gabbr2 cKO hippocampus is reminiscent of patients with epilepsy with a loss of dentate hilar neurons that govern dentate granule cell excitability." (PMID 41397015, 2025). "Pathogenic variants in the GABBR1 and GABBR2 genes, which encode the GB1 and GB2 subunits of GABABRs, are implicated in several neurological and developmental disorders, including epilepsy and autism." (PMID 38076211, 2023). "As GABA represents the main neurotransmitter in the brain, GABBR1 and/or GABBR2 have been implicated in the pathogenesis of various neurological or psychiatric disorders such as epilepsy, Huntington’s disease, Alzheimer’s disease, autism, and depression." (PMID 37762034, 2023). "Among these, epilepsy is a frequent condition in individuals with GABBR1 and GABBR2 variants, consistent with the increased excitation–inhibition ratio and seizure susceptibility observed in GBR-deficient mice." (PMID 40756990, 2025). "Protein-protein interaction (PPI) analysis indicated that the protein encoded by KCNJ15 directly interacts with the two epilepsy drug targets encoded by GABBR1 and GABBR2, further supporting the role of KCNJ15 in epilepsy." (PMID 40342929, 2025). "In disrupted GPCR signaling, impaired GABBR2’s function contributes directly to epilepsy in cortical malformations such as LIS." (PMID 40806509, 2025). "Interestingly, a similar Rett-like phenotype without epilepsy has been reported, which was associated with a missense variant in GABBR2 leading to elevated constitutive receptor activity." (PMID 38076211, 2023).
schizophrenia (16 papers, 2012 to 2026). A major psychotic disorder characterized by abnormalities in the perception or expression of reality. "GABBR2 on 9q22.1-q22.3 is a well-known gene, as a susceptibility locus for schizophrenia and another gene in this locus is reported to be associated with cognitive test measure." (PMID 22901090, 2012). "In addition, the loci for both GABBR1 (6p21.3) and GABBR2 genes (5q34) have been recognized as the susceptibility loci for schizophrenia." (PMID 34067760, 2021). "Of 1,183 genes that mapped to nominally significant DMPs, some were previously associated with BD or schizophrenia, including MLC1, ESR1, KCKN5, L1CAM, CPEB1 and GABBR2." (PMID 35922419, 2022). "Schizophrenia GMV deficits in the hippocampus, temporal gyrus, and cerebellum are associated with genetic factors such as SATB2, GABBR2, and CACNA1C." (PMID 35717212, 2022). "CpG sites conforming the black module were enriched in morphine addiction (GABBR2, GABRP and PDE4B), and polymorphisms of the PDE4B gene have been associated with susceptibility to schizophrenia." (PMID 34579086, 2021). "Fatemi and coworkers detected significant reduction in GABBR1 and GABBR2 protein level in the lateral cerebella and superior frontal cortex from patients with schizophrenia, bipolar disorder, and major depression when compared to healthy controls." (PMID 34067760, 2021). "Multiple pieces of evidence have linked CNTN2, CNTNAP2, GABBR2, and NTRK3 to neuropsychiatric disorders, including schizophrenia." (PMID 30323833, 2018). "Expression of GABAB receptor subunits 1 and 2 (GABBR1 and GABBR2) were reported to alter significantly in the lateral cerebellum of subjects with schizophrenia." (PMID 30341038, 2018). "Also, significant reductions in Gabbr1 and Gabbr2 gene expression were reported to be present in lateral cerebellum of subjects with schizophrenia, bipolar disorder, and major depression, providing further evidence of GABAergic dysfunction in these diseases." (PMID 33006978, 2020). "We prioritized 101 schizophrenia genes, including 15 that are targeted by approved or investigational drugs (e.g., DRD2, GRIN2A, CACNA1C, GABBR2)." (PMID 41639063, 2026). "Alterations in GABA and GABA receptor expression (including downregulation of GABBR2) in different regions of ASD brains have been proposed to be involved in the etiology, and cortical GABAergic dysfunction is common in schizophrenia and ADHD." (PMID 35268026, 2022). "In previous SNP level analyses, ERG, NEBL, CADPS2, GABBR2, and HDAC9 genes have been reported to be related with neuropsychiatric diseases such as BD, depression disorder, and schizophrenia." (PMID 22901090, 2012). "In the network, candidate genes with nominal significance such as ANKS1B, CNTN2, CNTNAP2, GABBR2, NCOR2, and NTRK3 also may be involved in the pathology of schizophrenia." (PMID 30323833, 2018). "The remained CADPS2, GABBR2, and DHAC9 genes are related with schizophrenia." (PMID 22901090, 2012).
depression (9 papers, 2012 to 2025). "Gamma-aminobutyric acid type B receptor subunit 2 was reported to implicate in a number of neuronal disorders, including cognitive impairments, nociception, anxiety, and depression." (PMID 34422926, 2021). "Relevant differentially methylated regions in the blood of patients with major depression significantly overlap with differentially methylated regions in the Brodmann area of the brain and yield three CpG pooling sites in the brain: GABBR2, RUFY3 and an intergenic region on chromosome 2." (PMID 37140907, 2023).
Epileptic encephalopathy (7 papers, 2021 to 2026). A condition in which epileptiform abnormalities are believed to contribute to the progressive disturbance in cerebral function. "GABBR2, in particular, is a crucial factor in neurodevelopmental phenotypes, with mutations being associated with Rett syndrome and epileptic encephalopathy." (PMID 39702044, 2024). "Pathogenic variants in GABBR2 have been associated with various neurological phenotypes, including epileptic encephalopathy, intellectual disability, autism, and Rett-like features." (PMID 38076211, 2023). "Furthermore, we introduced the epileptic encephalopathy-associated p.I705N variant into the mouse Gabbr2 gene to examine its impact on neuronal and network activity." (PMID 40994051, 2026). "In addition, several pathogenic variants in GABBR2 have been reported in patients with early infantile epileptic encephalopathy, Rett syndrome-like disorders and ASD." (PMID 34069769, 2021). "The monoallelic variants p.A567T, p.S695I and p.I705N in the GABBR2 gene, which encodes the GB2 subunit, have been associated with epileptic encephalopathy and Rett-like disorders." (PMID 40994051, 2026). "Genetic mutations responsible for human brain diseases such as Rett-like phenotype, infantile epileptic spasms, and epileptic encephalopathy were identified in GABBR2 (which encodes GB2), with most of them resulting in missense mutations in TM3 and TM6." (PMID 34866572, 2021). "Previous studies on GABBR2 missense variants have revealed a correlation between the phenotype, such as epileptic encephalopathy vs. Rett-like phenotype without seizures, and the type of the variant (gain or loss-of-function), as well as the severity of the dysfunction." (PMID 38076211, 2023).
Anxiety (6 papers, 2021 to 2026). Intense feelings of nervousness, tension, or panic often arise in response to interpersonal stresses. "GABBR2 has been implicated in the treatment of several neurological conditions, including pain, anxiety, and spasticity." (PMID 38675434, 2024). "Activation of GABBR2 subunits alleviates the anxiety-like behaviors by promoting the BDNF signaling pathway and reversing the surface expression of Kir3 channel surface expressions in rat hippocampus." (PMID 40927314, 2025). "Previous reports on the global Gabbr2 KO mice described hyperlocomotion, elevated anxiety-related behaviors, and spontaneous seizure activity." (PMID 41397015, 2025). "Activation of GABAB2 subunits has previously been reported to alleviate anxiety-like behavior in cerebral ischemic mice; conversely, the reduced expression of Gabbr2 may contribute to anxiety-like symptoms, such as fatigue and unresponsiveness." (PMID 41561482, 2026).
autism (6 papers, 2022 to 2025). Persistent deficits in social interaction and communication and interaction as well as a markedly restricted repertoire of activity and interest as well as repetitive patterns of behavior. "It has been suggested that decreased GABBR2 expression in the cerebellum and the variants in the GABBR2 gene may be effective in the neurobiological basis of autism." (PMID 40873676, 2025).
prostate carcinoma (5 papers, 2022 to 2025). A carcinoma that arises from epithelial cells of the prostate gland. "Previous studies have confirmed that the increased expression of GABBR2 is associated with the progression of prostate cancer, cholangiocarcinoma, and malignant melanoma." (PMID 41217541, 2025). "ITPR1 and GABBR2 may be associated with AD, and prostate cancer." (PMID 36506318, 2022). "In a more recent study, a microRNA miR-31-3p was shown to suppress the growth of prostate cancer cells via directly downregulating GABBR2 expression similarly in AR-positive and AR-negative lines." (PMID 37762034, 2023).
Alzheimer disease (4 papers, 2022 to 2025). A progressive, neurodegenerative disease characterized by loss of function and death of nerve cells in several areas of the brain leading to loss of cognitive function such as memory and language. "The authors found rare variants in the GABBR2 gene, which was identified with non-Alzheimer’s disease synaptic functioning, reinforcing the notion that short-term NOS inhibition affects synaptic functioning in non-pathological brain aging." (PMID 35892672, 2022).
breast carcinoma (4 papers, 2022 to 2025). "By analyzing a public database (i.e., The Cancer Genome Atlas (TCGA)), GABBR2 overexpression was linked to lower T and N staging categories and better prognosis in patients with breast cancer." (PMID 37762034, 2023). "There were seven shared hub nodes (FPR2, CXCR4, FPR1, CX3CL1, GPR37, GABBR2 and PLCB1) between metastatic breast cancer cell lines." (PMID 35045088, 2022). "Protein-protein interaction (PPI) analysis revealed seven shared (PLCB1, FPR1, FPR2, CX3CL1, GABBR2, GPR37, and CXCR4) hub genes between brain and lung metastasis in breast cancer." (PMID 35045088, 2022). "We show that pharmacological modulation of GABBR2 does not affect proliferation of tumour or non-neoplastic cells whilst its activation promotes migration and invasion of the tumour cells in keeping with previous finding in breast cancer." (PMID 39915814, 2025).
colon cancer (4 papers, 2020 to 2025). "However, irrespective of whether expression of GABAA or GABAB receptor subunits were altered in colon cancer, expression of particular receptor subtypes (GABRA1, GABRA5, GABRD, GABRE, GABRG1, GABRG3, GABBR1, and GABBR2) was significantly associated with poor clinical outcome." (PMID 38886975, 2024). "Then, we collected seven pairs of colon cancer tissues and detected the expression of GABARAP and GABBR2 in the tissues by qRT-PCR." (PMID 38105184, 2023). "A later study in a familial form of colon cancer also was able to zoom in to a region around 9q22.2-31.2, in which aside the gene of HABP4 only three other genes are found, which seem to be less likely candidates for oncoproteins or tumor suppressors (ZNF367, GABBR2 and GALNT12)." (PMID 33245729, 2020).
glioblastoma (4 papers, 2017 to 2025). The most malignant astrocytic tumor (WHO grade IV). "Our study has identified two novel druggable target genes, SMOX and GABBR2, which are differentially regulated and expressed in normal and neoplastic stem cells in glioblastoma." (PMID 39915814, 2025). "Leveraging the GBmap dataset, we show that GABBR2 is preferentially expressed in neurons, possibly implying a role in neuronal specification in glioblastoma." (PMID 39915814, 2025). "SMOX and GABBR2 are novel patient-specific epigenetically regulated potentially druggable targets in glioblastoma." (PMID 39915814, 2025). "Therefore, targeting GABBR2 could represent a promising therapeutic strategy to disrupt key pathways involved in glioblastoma progression." (PMID 39915814, 2025). "Comparative analysis of switching chromatin states between GIC and iNSC identified novel pharmacologically targetable genes, including SMOX and GABBR2 in a subgroup of glioblastoma, which could be further explored as new therapeutic approaches to counteract glioblastoma invasiveness." (PMID 39915814, 2025).
Intellectual disability (4 papers, 2022 to 2026). "Here, we investigated the functional impact of seven de novo missense variants in GABBR1 and GABBR2 identified in individuals with autism spectrum disorder, intellectual disability, and/or attention deficit/hyperactivity disorder." (PMID 41803176, 2026).
Rett-like syndrome (4 papers, 2019 to 2025). "Pathogenic variants in GABBR2 were initially identified in individuals with DEE59 or with clinical features resembling atypical Rett syndrome." (PMID 40756990, 2025). "Other hub genes (GABBR2, GRM7, MEF2C, SCN2A, KMT2C, and DAGLA) dysfunction have been reported to contribute to ASD and other psychiatric disorders such as Attention-Deficit Hyperactivity Disorder (ADHD), Huntington’s disease, and Rett-syndrome." (PMID 31649562, 2019).
alcohol dependence (3 papers, 2013 to 2022). Physical and psychological dependence on alcohol. "Polymorphism of Gabbr2 is associated with nicotine and alcohol dependence, and increased transcription of Gabbr2 is observed in the PFC of nicotine-treated and alcohol-addicted animals." (PMID 23536882, 2013). "GABRB1 (4p12) and GABBR2 (9q22.33, 143 kb upstream of rs73655199) are major neurotransmitters in the vertebrate brain, representing ligand-gated ion channels and have been shown to associate with alcohol dependence." (PMID 29912962, 2018).
Cognitive impairment (3 papers, 2021 to 2025). Abnormal cognition is characterized by deficits in thinking, reasoning, or remembering. "Moreover, GABBR2 was decreased in Braak stages 3–4, stages referring to mild cognitive impairment, compared with stages 0–2." (PMID 40927314, 2025).
autism spectrum disorder (2 papers, 2023 to 2026). A spectrum of developmental disorders that includes autism, and Asperger syndrome. "Here we present a 7-year-old boy with Level 3 Autism Spectrum Disorder who carries a de novo heterozygous missense GABBR2 p.Arg212Gln variant." (PMID 38076211, 2023). "In this study, we used the MD pipeline to analyze the GABBR2 p.Arg212Gln variant in a child diagnosed with Level 3 Autism Spectrum Disorder." (PMID 38076211, 2023).